CLSPN (claspin)
Diseases named in the same sentence as CLSPN in open-access papers (continued):
Sharing a sentence is not in itself a finding about the gene and the disease.
hepatocellular carcinoma (4 papers, 2016 to 2025). A malignant tumor that arises from hepatocytes. "Heterozygous CLSPN KO mice were also more prone to develop acute liver injury induced by N-nitrosodiethylamine (DEN), a DNA alkylating agent that causes DNA and hepatocyte damage, as well as non-alcoholic fatty liver disease and hepatocellular carcinoma." (PMID 41009395, 2025). "In an integrated analysis of microRNA networks in hepatocellular carcinoma (HCC), CLSPN was found to be part of a set of genes regulated by miRNA-424, and low CLSPN expression was correlated with better overall patient survival, functioning as a prognostic marker for HCC." (PMID 41009395, 2025). "Reduced Claspin levels result in increased liver damage and tumourigenesis in the DEN model of hepatocellular carcinoma." (PMID 36240068, 2022). "They observed that mice lacking Claspin have a myriad of defects, such as impaired female fertility and an increase in the disease states lymphoid hyperplasia, non-alcoholic fatty liver disease, and hepatocellular carcinoma following liver damage by partial hepatectomy or the DNA-damaging agent DEN." (PMID 36416754, 2022).
melanoma (4 papers, 2014 to 2023). A malignant, usually aggressive tumor composed of atypical, neoplastic melanocytes. "It has been previously reported that c-Myc and claspin regulate cell proliferation but their association with HH signaling and melanoma progression is largely unknown." (PMID 31820036, 2020). "In melanoma cells, it was confirmed that there is a decrease of the activation of these 3 upregulated proteins (cleaved-Caspase-3, Claspin and HO-1) after the cells were exposed to BOZ + ALA combination compared to the BOZ-treated cells." (PMID 32868799, 2020). "Downregulation of apoptotic proteins such as HO-1 and Claspin along with the inhibition of the cleavage of Caspase-3 indicated the proteomic background of the altered responsiveness of the melanoma cells exposed to BOZ + ALA." (PMID 32868799, 2020). "In this work, as an end target of the HA-IHH-c-Myc-claspin signaling cascade, we have found that claspin follows a similar tissue staining pattern as HA during melanoma progression." (PMID 31820036, 2020). "The IHH-c-Myc-claspin axis may help a normal keratinocyte (HaCaT) and a melanoma cell line (WM115) to gain tumorigenic potential, such as increased proliferation; this effect may be due to an enhanced G1/S phase transition and EMT." (PMID 31820036, 2020). "In this study we could demonstrate, that treatment with BOZ led to Caspase-3 and Heme Oxygenase-1 (HO-1) activation in both cell lines, and could upregulate the expression of Claspin only in melanoma cells." (PMID 32868799, 2020). "Interestingly, this staining pattern of claspin in different stages of melanoma corresponded to HA staining in melanoma progression." (PMID 31820036, 2020). "Interestingly one recent report showed that the CDC42 homologue RhoJ and its effector PAK1 modulate ATR activity via degradation of claspin after DNA damage thereby uncoupling ATR from Chk1; moreover RhoJ appears to be upregulated in advanced melanoma." (PMID 24416382, 2014).
renal cell carcinoma (4 papers, 2021 to 2025). "Claspin expression was also upregulated in renal cell carcinoma and urothelial cancer and directly correlated with tumor grade and stage, nuclear grade, and vascular invasion, and was associated with worse prognosis." (PMID 41009395, 2025). "What is more, our previous study on renal cell carcinoma showed that claspin was involved in Akt and Erk1/2 phosphorylation." (PMID 34240817, 2021). "Claspin expression is frequently observed in EGFR-positive renal cell carcinoma cells, which may be due to the proliferation signaling induced through EGFR." (PMID 41009395, 2025).
leukemia (3 papers, 2023 to 2025). A malignant (clonal) hematologic disorder, involving hematopoietic stem cells and characterized by the presence of primitive or atypical myeloid or lymphoid cells in the bone marrow and the blood. "Beyond leukemia, CLSPN has been implicated in the progression of solid tumors." (PMID 41424711, 2025). "CLSPN interact with DNMT1 to mediate decitabine response in leukemia." (PMID 41424711, 2025).
pancreatic cancer (3 papers, 2016 to 2025). "Herein, we provided evidence that silencing of Claspin in pancreatic cancer cells led to cellular proliferation inhibition and apoptosis." (PMID 38110764, 2023). "Our study highlighted a novel mechanism underlying celastrol-induced cellular proliferation inhibition and apoptosis in pancreatic cancer cells via m6A-YTHDF3-mediated downregulation of Claspin and Bcl-2." (PMID 38110764, 2023). "Mechanistically, we demonstrated that celastrol-induced cellular proliferation inhibition and apoptosis in pancreatic cancer cells by downregulating Claspin and Bcl-2 expression in an m6A-YTHDF3-mediated manner." (PMID 38110764, 2023). "Based on the well illustration of the role of Bcl-2 in cancer progression, we focused on the role of Claspin in celastrol-treated pancreatic cancer cells." (PMID 38110764, 2023). "Here, we observed the up-regulation of Claspin and Bcl-2 in pancreatic cancer cell lines when compared with those in normal pancreatic cells." (PMID 38110764, 2023). "It is notable that the elevated abundance of Claspin and Bcl-2 was shown in human pancreatic cancer cell lines (PANC-1, SW1990, AsPC-1, and BxPC-3) when compared to those in normal pancreatic cells (HPDE6C) as measured by Western blotting." (PMID 38110764, 2023). "Therefore, we supposed that celastrol treatment induced cell proliferation inhibition and apoptosis probably by downregulating Claspin in pancreatic cancer cells." (PMID 38110764, 2023). "Notably, we found that celastrol treatment mediated the reduction of m6A levels of Claspin and Bcl-2 mRNA by downregulating METTL3, leading to the degradation of Claspin and Bcl-2 mRNA in pancreatic cancer cells." (PMID 38110764, 2023). "Moreover, our results indicated that celastrol treatment downregulated METTL3 and decreased m6A levels of Claspin and Bcl-2 mRNA, leading to the degradation of Claspin and Bcl-2 mRNA in pancreatic cancer cells." (PMID 38110764, 2023). "Claspin has primarily been characterized as an adaptor protein that participated in the modulation of cell cycle progression, DNA damage and repair, and apoptosis, however, little is known about the role of Claspin in pancreatic cancer." (PMID 38110764, 2023). "Moreover, we uncovered that overexpression of METTL3 partially reversed celastrol-induced downregulation of Claspin and Bcl-2, which provided the causative link between RNA m6A modification and the expression of Claspin and Bcl-2 induced by celastrol treatment in pancreatic cancer cells." (PMID 38110764, 2023). "Additionally, we noted that celastrol treatment facilitated the mRNA decay of Claspin and Bcl-2, suggesting that celastrol-mediated decrease of the m6A modification might trigger the mRNA degradation of Claspin and Bcl-2 in pancreatic cancer cells." (PMID 38110764, 2023). "We conclude that Claspin and associated regulatory factors including Mre11 and Chk1 could be therapeutically targeted by E1B19K-deleted oncolytic viruses and/or novel inhibitors to better manage treatment-insensitive pancreatic cancers in particular." (PMID 26872382, 2016). "Taken together, our data clearly indicated that celastrol treatment downregulated Claspin and Bcl-2, at least in part, in an m6A-YTHDF3-mediated manner in pancreatic cancer cells." (PMID 38110764, 2023). "Furthermore, we noted that YTHDF3 overexpression partially rescued celastrol-induced downregulation of Claspin and Bcl-2, and abrogated the celastrol-mediated suppression of cell proliferation and cell cycle progression, and the induction of apoptosis in celastrol-treated in pancreatic cancer cells." (PMID 38110764, 2023). "We demonstrated that celastrol treatment reduced total RNA m6A modification in pancreatic cancer cells by down-regulating METTL3 expression, especially decreased Claspin and Bcl-2 mRNA m6A modification, which induced the Claspin and Bcl-2 mRNA decay." (PMID 38110764, 2023).
pancreatic cancer (continued). "Further study revealed that celastrol treatment downregulated Claspin and Bcl-2 in an m6A-YTHDF3-mediated manner, which providing a novel mechanism for the therapeutic application of celastrol in pancreatic cancer." (PMID 38110764, 2023). "Specifically, Bcl-2, Claspin, METTL3 and YTHDF3 were identified as the potential targets of celastrol treatment in pancreatic cancer cells." (PMID 38110764, 2023). "Collectively, our data clearly indicated that Claspin and Bcl-2 might be the targets of YTHDF3, and celastrol treatment downregulated Claspin and Bcl-2 in an m6A-YTHDF3-mediated manner in pancreatic cancer cells." (PMID 38110764, 2023). "Based on these data, it can be concluded that celastrol treatment decreased the global RNA m6A modification, especially reduced the mRNA m6A modification of Claspin and Bcl-2 probably by downregulating METTL3, leading to the downregulation of Claspin and Bcl-2 in pancreatic cancer cells." (PMID 38110764, 2023). "Collectively, our findings indicated that Claspin, Bcl-2, METTL3, and YTHDF3 might be the potential targets of celastrol treatment in pancreatic cancer cells." (PMID 38110764, 2023). "Furthermore, we revealed that celastrol treatment downregulated Claspin and Bcl-2, at least in part, in an m6A-YTHDF3-mediated manner in pancreatic cancer cells." (PMID 38110764, 2023). "In summary, the findings present here provided in vitro and in vivo evidences demonstrating that downregulation of Bcl-2, Claspin, METTL3 and YTHDF3 was involved in celastrol-induced cellular proliferation inhibition, cell cycle arrest and apoptosis in pancreatic cancer cells." (PMID 38110764, 2023).
squamous cell carcinoma (3 papers, 2012 to 2025). A carcinoma arising from squamous epithelial cells. "Benevolo and colleagues assessed Claspin expression in cervical biopsy samples of increasing malignancy, including normal tissues, Cervical Intraepithelial Neoplasias (CIN) 1, 2, and 3, and squamous cell carcinomas, which represent different steps of malignant transformation." (PMID 41009395, 2025). "They found that Claspin expression increased with malignancy, being absent or scarce in normal tissue and significantly upregulated in squamous cell carcinomas." (PMID 41009395, 2025).
urothelial carcinoma (3 papers, 2023 to 2025). A malignant neoplasm derived from the transitional epithelium of the urinary tract (urinary bladder, ureter, urethra, or renal pelvis). "Over-expression of Claspin also seems to underlie acquired resistance to cisplatin in urothelial carcinoma." (PMID 41009395, 2025). "Moreover, CLSPN overexpression has been linked to cisplatin resistance in urothelial carcinoma, highlighting its potential as a target for immunotherapy." (PMID 41424711, 2025). "To address this hypothesis, we silenced CLSPN expression by siRNA and evaluated cell survival and apoptosis in UROtsa (benign) and 5637 (urothelial carcinoma) cells." (PMID 36902377, 2023). "Interestingly, CLSPN knockdown inhibited apoptosis and increased cell survival in UROtsa cells (benign), while CLSPN knockdown enhanced apoptosis and decreased cell survival in 5637 cells (urothelial carcinoma)." (PMID 36902377, 2023).
acute myeloid leukemia (2 papers, 2016 to 2025). Acute myeloid leukemia (AML) is a group of neoplasms arising from precursor cells committed to the myeloid cell-line differentiation. "In a previous study, we showed that mistletoe extracts similarly reduced CLSPN expression in acute myeloid leukemia cells, where extracts also induced apoptosis and inhibited proliferation." (PMID 27589063, 2016). "CLSPN has emerged as a key player in the mechanism of action of decitabine, a drug used to treat myelodysplastic syndrome (MDS) and acute myeloid leukemia (AML)." (PMID 41424711, 2025).
Fanconi anemia (2 papers, 2020 to 2025). Fanconi anemia (FA) is a hereditary DNA repair disorder characterized by progressive pancytopenia with bone marrow failure, variable congenital malformations and predisposition to develop hematological or solid tumors. "We found that the knockdown of TAPIRs leads to the suppression of genes essential for the DNA-damage response, as there are BRCA1 (breast cancer 1, early-onset), CHEK1 (Checkpoint kinase 1), CLSPN (Claspin), and genes encoding proteins of the Fanconi anemia pathway." (PMID 32365858, 2020).
lung adenocarcinoma (2 papers, 2023 to 2025). A carcinoma that arises from the lung and is characterized by the presence of malignant glandular epithelial cells. "Knockdown CLSPN significantly inhibited cancer cell proliferation and cell cycle related cyclin-dependent kinase (CDK) family and Cyclin family expression in LUAD (lung adenocarcinoma) both in vitro and in vivo experiments." (PMID 37268895, 2023).
non-small cell lung carcinoma (2 papers, 2024 to 2025). A group of at least three distinct histological types of lung cancer, including non-small cell squamous cell carcinoma, adenocarcinoma, and large cell carcinoma. "In addition, over-expression of POLQ, PLK1, RAD51, CDC6, and CLSPN was found to correlate with worse prognosis in non-small cell lung cancer." (PMID 41009395, 2025). "As an example, in early- to mid-stage non-small cell lung cancer, Claspin was only one of a set of five genes (POLQ, PLK1, RAD51, CDC6, and CLSPN) encoding proteins involved in the maintenance of genome stability that were found to be consistently upregulated and associated with poor survival." (PMID 41009395, 2025).
oral cancer (2 papers, 2024 to 2025). "Attempts have been made to obtain insight into the role of CLSPN gene polymorphisms in oral cancer through the analysis of this study." (PMID 38256171, 2024). "Our study is the first to provide evidence on the interactive effect of CLSPN gene polymorphisms and alcohol drinking on the progression of oral cancer." (PMID 38256171, 2024). "On the basis of our analysis of the Cancer Genome Atlas dataset, we found that higher CLSPN levels were associated with poorer cell differentiation in oral cancers." (PMID 38256171, 2024). "Recently, CLSPN polymorphisms were shown to contribute to oral cancer progression, namely cell undifferentiation, which may be due to Claspin’s function in the transmission of the histone code into daughter cells." (PMID 41009395, 2025). "CLSPN genotypes are associated with oral cancer, but the literature on this association is limited." (PMID 38256171, 2024). "As a result, the goal of this study is to investigate the correlation between CLSPN genotypes and oral cancers’ development." (PMID 38256171, 2024). "In this study, we provide the first evidence showing that CLSPN SNPs contribute to oral cancer." (PMID 38256171, 2024).
ovarian carcinoma (2 papers, 2022 to 2024). A malignant neoplasm originating from the surface ovarian epithelium. "Mutations in Claspin have been described in familial and sporadic breast and ovarian cancers." (PMID 36240068, 2022).
ovarian clear cell cancer (2 papers, 2018 to 2023). An invasive malignant neoplasm that arises from the ovary and is characterized by a predominance of clear and hobnail malignant epithelial cells. "Thus, deubiquitination of Claspin caused by USP28 contributes to cell cycle arrest, which maintains ovarian clear cell carcinoma cell viability in response to a genotoxic stress." (PMID 36879346, 2023). "A previous study showed that, in ovarian clear cell carcinoma cells with DNA damage, knockdown of USP28 reduced both Claspin and Chk1 levels." (PMID 36879346, 2023).
adenoma (1 paper, 2022). A neoplasm arising from the epithelium. "Together these data suggest that either a loss of Claspin could be responsible for an earlier onset of tumourigenesis in the DEN model and/or, the loss could increase the probability that cells undergo malignant transformation, increasing adenoma–carcinoma progression." (PMID 36240068, 2022).
Adrenocortical carcinoma (1 paper, 2023). "Kaplan–Meier survival curves revealed that high CLSPN expression was obviously related to poor OS in ACC (Adrenocortical carcinoma), KICH, KIRP, LUAD, MESO (mesothelioma), PAAD (pancreatic adenocarcinoma), SKCM (skin cutaneous melanoma), UVM (uveal melanoma)." (PMID 37268895, 2023).
bone osteosarcoma (1 paper, 2019). A usually aggressive malignant bone-forming mesenchymal neoplasm arising from the bone. "We examined the function of the Claspin APDE/A mutant for checkpoint activation in U2OS cells (human bone osteosarcoma epithelial cells) as well." (PMID 31889509, 2019).
colon cancer (1 paper, 2019). "We, therefore, focused subsequent analyses on the function of Claspin and Timeless, using HCT116 colon cancer cells as an experimental model." (PMID 30796221, 2019). "Our data indicate that the abundance of TopBP1 and BRCA1 correlates with Claspin, Timeless, and CHK1 in colon cancer cell lines, which would be consistent with the latter hypothesis." (PMID 30796221, 2019).
COVID-19 (1 paper, 2025). A disease caused by infection with severe acute respiratory syndrome coronavirus 2. "Five genes, including PAFAH2, LINC02915, CLSPN, EIF4G1 and IFI27, were predictors of both COVID-19 and RSV-LRTI hospitalization." (PMID 41279033, 2025).
Ewing sarcoma (1 paper, 2016). A small round cell tumor that lacks morphologic, immunohistochemical, and electron microscopic evidence of neuroectodermal differentiation. "Here we demonstrate that reconstituting the aqueous and triterpene components from mistletoe in the viscumTT extract synergistically induces caspase-dependent apoptosis associated with CLSPN, MCL1, BIRC5 and XIAP downregulation in Ewing sarcoma cell lines in vitro and primary cells ex vivo." (PMID 27589063, 2016).
fatty liver disease (1 paper, 2022). A reversible condition wherein large vacuoles of triglyceride fat accumulate in liver cells via the process of steatosis. "Taken together our data demonstrate for the first time that Claspin can function as a tumour suppressor and prevent both cancer development and fatty liver disease." (PMID 36240068, 2022).
head and neck carcinoma (1 paper, 2024). A carcinoma that arises from the head and neck region. "Among the 60 DETGs, genes such as TFAP2A, CLSPN, RASEF, HIST1H3H, AKT3, and ITPR1 were associated with metastasis to secondary sites, including the lungs, and with head and neck carcinoma." (PMID 39095857, 2024).
head and neck squamous cell carcinoma (1 paper, 2024). A squamous cell carcinoma that arises from any of the following anatomic sites: lip and oral cavity, nasal cavity, paranasal sinuses, pharynx, larynx, and salivary glands. "Moreover, the downregulation of Claspin was found in head and neck squamous cell carcinoma (HNSCC) after triple therapy." (PMID 38256171, 2024).
lymph node metastasis (1 paper, 2021). "In a public database, high CLSPN expression was associated with poor PSA relapse‐free prognosis, Gleason score, T stage, lymph node metastasis, CRPC, and metastatic PCa." (PMID 34240817, 2021). "From the TCGA data set, the CLSPN expression level increased significantly with increasing Gleason Scores and T stages and was higher in the group with lymph node metastases than that without metastases." (PMID 34240817, 2021).